TRIB1AL (TRIB1 associated lncRNA)
Synonyms: TRIBAL
Gene: Long non-coding RNA gene on chromosome 8 (125,466,939 to 125,541,850, forward strand). Ensembl gene ENSG00000253111.
Diseases named in the same sentence as TRIB1AL in open-access papers:
TRIB1AL is named in the same sentence as 8 diseases in open-access papers, as found by Europe PMC text mining. Sharing a sentence is not in itself a finding about the gene and the disease.
TRIB1AL shares sentences with these, for which no sentence is quoted: atherosclerosis (1 paper); dyslipidemia (1); fatty liver (1); hepatoblastoma (1); hepatoma (1); Insulin resistance (1); Obesity (1); type 2 diabetes (1).